SKP2 (S-phase kinase associated protein 2)
Diseases named in the same sentence as SKP2 in open-access papers (continued):
Sharing a sentence is not in itself a finding about the gene and the disease.
prostate tumor (9 papers, 2014 to 2026). "TRIM33 is an oncogenic coactivator that drives prostate tumor growth by stabilizing AR from S-phase kinase associated protein 2 (Skp2)–mediated degradation." (PMID 38104650, 2024). "Our findings in vitro on the SKP2 deficiency-promoted shuttling of JARID1B protein encouraged us to validate the phenomenon in prostate tumors of mice." (PMID 25596733, 2015). "Remarkably, Skp2 deficiency significantly suppressed the growth of prostate tumors of Ptenpc−/−; Trp53pc−/− mice." (PMID 25596733, 2015). "However, Skp2 loss significantly increased Foxa1 levels in prostate tumors of Ptenpc−/−; Trp53pc−/−; Skp2+/− and Ptenpc−/−; Trp53pc−/−; Skp2−/− mice in a dose‐dependent manner, indicating an essential role for Skp2 in Foxa1 regulation." (PMID 37491794, 2023). "TRIM33 also drives prostate tumor growth by stabilizing Skp2-mediated androgen receptor degradation." (PMID 39389957, 2024). "We then proceeded to investigate the effects of Skp2 KO in the ubiquitin‐mediated regulation of Foxa1 in prostate tumors of conditional knockout (pc−/−) Ptenpc−/−; Trp53pc−/−; Skp2−/− mutant mice." (PMID 37491794, 2023). "Targeting post‐translational regulatory mechanisms for FOXA1 through SKP2 inhibition (SZL P1‐41) reduced prostate tumor proliferation, and restored luminal phenotypes and FOXA1 levels, supporting enhanced therapeutic sensitivity in advanced stages of PCa." (PMID 37491794, 2023). "Worthy of note, Skp2 ablation with concurrent enhanced levels of Foxa1 in Ptenpc−/−; Trp53pc−/−; Skp2−/− mice resulted in decreased tumor burden by suppressing prostate tumor proliferation." (PMID 37491794, 2023). "Prostate tumors in Ptenpc−/−; Trp53pc−/− mice developed microinvasion with cells in atypical nucleus, while age-matched Ptenpc−/−; Trp53pc−/−; Skp2−/− mice showed the less severe abnormality of prostate glands with PIN lesions." (PMID 25596733, 2015). "In contrast, prostate tumors of Ptenpc−/−; Trp53pc−/−; Skp2−/− mice were much smaller with visible forms of glandular structures as HGPIN, and few cells displayed atypical nucleus." (PMID 25596733, 2015). "In addition, IHC results also showed that TRAF6 levels were strikingly increased in prostate tumors of Ptenpc−/−; Trp53pc−/−; Skp2−/− mice, as compared to that of Ptenpc−/−; Trp53pc−/− mice." (PMID 25596733, 2015). "In agreement, Skp2 deficiency resulted in an increase of JARID1B ubiquitination and in turn a reduction of H3K4me3, and induced senescence through JARID1B accumulation in nucleoli of PCa cells and prostate tumors of mice." (PMID 25596733, 2015). "Surprisingly, gene expression of CDK7 negatively correlated to CDK2, SKP2, and CCNA2 in both GSE6919 and Singh prostate tumor datasets." (PMID 25271736, 2014). "Our results showed that JARID1B and FBL proteins are co-localized in a majority of epithelial cells in prostate tumors of Ptenpc−/−; Trp53pc−/−; Skp2−/− mice, but not in that of Ptenpc−/−; Trp53pc−/− mice." (PMID 25596733, 2015). "The cellular senescence was detected in prostate tumors of Ptenpc−/−; Trp53pc−/−; Skp2−/− mice, but not in that of Ptenpc−/−; Trp53pc−/− mice." (PMID 25596733, 2015).
prostate tumor (continued). "Indeed, analysis of oncomine data indicated that gene expression level of SKP2, CDK2, and CCNA2 correlated positively well in both GSE6919 and Singh prostate tumor datasets." (PMID 25271736, 2014).
breast tumor (8 papers, 2012 to 2024). "Sirt7 overexpression suppresses S-phase kinase-associated protein 2 (Skp2)-Culin1-F-box (SCF) E3 ligase-mediated AKT ubiquitination and TGF-β/SMAD family member 4 (SMAD4) signaling, thus antagonizing the growth of breast tumors and metastasis to distal organs." (PMID 37676263, 2024). "Consistent with this, we observed an inverse correlation between Skp2 and E-cadherin expression in clinical breast tumor samples." (PMID 23230084, 2012). "Moreover, DLL1 downregulation caused a 2-fold reduction in the expression levels of CDC25A and SKP2 genes, which are often overexpressed in breast tumors and involved in BC pathogenesis." (PMID 31107884, 2019). "Furthermore, Skp2 deletion was associated with Herceptin sensitivity and suppression of Skp2 expression sensitized HER2-positive breast tumors to Herceptin treatment." (PMID 28335434, 2017). "This relationship is recapitulated in studies showing that absence of Cdh1 caused an increase in Skp2 and increased breast tumor growth in a xenograft model whereas elevation of Cdh1 had the opposite effect." (PMID 23029392, 2012).
esophageal squamous cell carcinoma (8 papers, 2011 to 2025). Esophageal squamous cell carcinoma (ESCC) is a type of esophageal carcinoma (EC) that can affect any part of the esophagus, but is usually located in the upper or middle third. "Furthermore, the anti-apoptotic role of p62 causes activation of the p62-PKCiota-SKP2 pathway in esophageal squamous cell carcinoma (ESCC) through stabilizing SKP2 under serum starvation condition." (PMID 29738493, 2018). "The correlation of S-phase kinase–associated protein 2 (Skp2) with metastasis and prognosis in esophageal squamous cell carcinoma (ESCC) is controversial." (PMID 22533738, 2012). "In addition, miR-186 suppressed proliferation and stimulated apoptosis by targeting Skp2 in esophageal squamous cell carcinoma." (PMID 33621206, 2021). "Additionally, induced expression of Skp2 and paralleled Rad51 expression promoted radiation resistance of esophageal squamous cell carcinoma EC9706 cells." (PMID 34068643, 2021). "Dual inhibition of the PI3K/AKT/mTOR pathway with MK2206 and BEZ235 caused cell cycle arrest and enhanced apoptosis through the downstream effectors SKP2, MCL-1, and cyclin D1 in esophageal squamous cell carcinoma cells." (PMID 33659215, 2020). "Radiation-induced Skp2 expression and a negative correlation with survival rates of patients were found in esophageal squamous cell carcinoma patients." (PMID 34068643, 2021).
gastrointestinal stromal tumor (8 papers, 2008 to 2025). "The purpose of this study was to clarify the prognostic significance of Jab1, p16, p21, p62, Ki67 and Skp2 expression in non-gastrointestinal stromal tumor (non-GIST) STS." (PMID 23071715, 2012). "The purpose of this study is to clarify the prognostic significance of expression of Skp2 related to age, gender and female steroid hormone receptors (ER and PGR) in non-gastrointestinal stromal tumor (non-GIST) STS." (PMID 23497154, 2013).
pulmonary fibrosis (7 papers, 2018 to 2025). Chronic progressive interstitial lung disorder characterized by the replacement of the lung tissue by connective tissue, leading to progressive dyspnea, respiratory failure, or right heart failure. "Altogether, these results suggested that Skp2-inhibition by SZL-P1-41 as well as Skp2-deficiency inhibited progression of BLM-induced pulmonary fibrosis." (PMID 29415439, 2018). "In this study, pathological evaluations using Ashcroft and fibrosis scores indicated that the progression of BLM-induced pulmonary fibrosis was significantly attenuated in Skp2-deficient mice." (PMID 29415439, 2018). "Herein, we explored the molecular mechanism by which microRNA‐205‐5p (miR‐205‐5p) affects the autophagy of alveolar macrophages (AMs) and pulmonary fibrosis in mice with silicosis through the E2F transcription factor 1 (E2F1)/S‐phase kinase‐associated protein 2 (SKP2)/Beclin1 axis." (PMID 34428336, 2021). "Similarly, in the bleomycin-induced pulmonary fibrosis model, accumulation of both collagen A1 and fibronectin and the score of pulmonary fibrosis are reduced by Skp2-deficiency." (PMID 34198949, 2021). "Because fibrotic changes began one week after BLM-injection and were more evident and extensive after two weeks, we evaluated the effects of Skp2-deficiency at a relatively early stage of pulmonary fibrosis progression using Skp2-deficient mice two weeks after BLM-injection." (PMID 29415439, 2018). "To test this hypothesis, we investigated whether Skp2-deficiency affects fibrotic progression in the BLM-induced mouse pulmonary fibrosis model." (PMID 29415439, 2018). "In the BLM-mediated fibrosis model, Skp2-deficient mice promote mesenchymal fibroblast proliferation and EMT, during the advancement of pulmonary fibrosis by mediating P27 degradation." (PMID 40901482, 2025). "The current study elucidated that miR‐205‐5p targeted E2F1, thereby inhibiting SKP2‐mediated Beclin1 ubiquitination to promote macrophage autophagy and inhibit pulmonary fibrosis in mice with silicosis." (PMID 34428336, 2021). "Recently, SKP2 was reported as a potential molecular target for human pulmonary fibrosis as its inhibition reduces the pulmonary fibrosis in silicosis." (PMID 34428336, 2021). "We silenced or overexpressed miR‐205‐5p, E2F1, SKP2 and Beclin1 to investigate their potential roles in pulmonary fibrosis in vivo and autophagy in vitro." (PMID 34428336, 2021). "p27 degradation mediated by the SCF-type E3 ligase, Skp2, contributes to the progression of pulmonary fibrosis by promotion of either mesenchymal fibroblast proliferation, EMT, or both." (PMID 34198949, 2021). "Either way, our results suggest that Skp2 is a novel molecular target for human pulmonary fibrosis including IPF." (PMID 29415439, 2018). "Our study suggests that Skp2 is a potential molecular target for human pulmonary fibrosis including IPF." (PMID 29415439, 2018). "Therefore, the afore‐mentioned findings revealed that miR‐205‐5p inhibited pulmonary fibrosis via the E2F1/SKP2/Beclin1 axis." (PMID 34428336, 2021). "Finally, the cell and murine models suggested that miR‐205‐5p impeded SKP2‐mediated Beclin1 ubiquitination to promote Beclin1‐mediated autophagy and suppress pulmonary fibrosis." (PMID 34428336, 2021). "As SKP2 might promote the ubiquitination of Beclin1,21 we initially analysed the microarray data set GSE110711 of mice with silicosis in the GEO database by R language and identified that the SKP2 gene was highly expressed in the setting of pulmonary fibrosis." (PMID 34428336, 2021). "As SKP2 has been reported to mediate the ubiquitination of Beclin1,21 we speculated the involvement of miR‐205‐5p in autophagy and pulmonary fibrosis through mediating the E2F1/SKP2/Beclin1 axis." (PMID 34428336, 2021). "Alternatively, if combined inhibition of the degradation of several Skp2 targets is required, inhibitors of the Skp1/Skp2 interaction or inhibitors of Skp2 expression may be effective against pulmonary fibrosis." (PMID 29415439, 2018).
pulmonary fibrosis (continued). "Moreover, we confirmed that the Skp2 inhibitor suppressed pulmonary fibrosis by evaluating the expression of fibrosis markers." (PMID 29415439, 2018). "Based on these findings, we speculated that Skp2 might also contribute to pulmonary fibrosis and be a potential molecular target for IPF therapy." (PMID 29415439, 2018). "We evaluated whether Skp2 is a potential molecular target for IPF using the BLM-induced pulmonary fibrosis mouse model." (PMID 29415439, 2018). "As these results suggested that inhibiting Skp2 might be effective for BLM-induced pulmonary fibrosis, we next performed a treatment experiment using the Skp2 inhibitor SZL-P1-41." (PMID 29415439, 2018). "We cannot deny the contribution of other Skp2 targets proteins in BLM-induced pulmonary fibrosis." (PMID 29415439, 2018). "Furthermore, a small molecule Skp2 inhibitor (SZL-P1-41) significantly inhibited progression of pulmonary fibrosis and the accumulation of fibrosis markers." (PMID 29415439, 2018). "Therefore, we performed p27 immunostaining in the murine lung sections to determine the involvement of p27 as a Skp2 target during the progression of BLM-induced lung fibrosis." (PMID 29415439, 2018). "If p27 is the most important Skp2 target in pulmonary fibrosis, inhibitors of the Skp2/p27 interaction and Skp2/Cks1 interaction, which are expected to be selective inhibitors of p27-degradation, may be suitable for targeted therapy." (PMID 29415439, 2018). "Interestingly, the decreased body weight in BLM-infused mice was recovered by SZL-P1-41 treatment, supporting the conclusion that Skp2 inhibition attenuates the progression of pulmonary fibrosis." (PMID 29415439, 2018). "We examined whether disrupting Skp2 suppressed pulmonary fibrosis in a bleomycin (BLM)-induced mouse model and found that pulmonary fibrosis was significantly suppressed in Skp2-deficient mice compared with controls." (PMID 29415439, 2018). "Moreover, p27 levels were increased by the SZL-P1-41 treatment, suggesting p27 may be an important Skp2 target for BLM-induced pulmonary fibrosis." (PMID 29415439, 2018). "Skp2, part of the SCF-Skp2 ubiquitin ligase complex, also plays a role in increasing mesenchymal fibroblasts in response to bleomycin, affecting pulmonary fibrosis progression." (PMID 40901482, 2025). "Our findings revealed that miR‐205‐5p impaired pulmonary fibrosis and E2F1/SKP2/Beclin1 axis was responsible for the role of miR‐205‐5p in such process." (PMID 34428336, 2021). "The result suggested that SZL-P1-41 inhibited p27 degradation in BLM-induced pulmonary fibrosis, further demonstrating that SZL-P1-41 inhibited the Skp2 E3 ligase activity in the model." (PMID 29415439, 2018). "To further explore the upstream mechanism of SKP2, we initially analysed the microarray data set GSE110711 in the GEO database using R language and screened out 3246 differentially expressed genes in pulmonary fibrosis." (PMID 34428336, 2021). "Additionally, miR‐205‐5p agomir suppressed the pulmonary fibrosis in mice with silicosis, while Lenti‐E2F1, Lenti‐SKP2 or siBeclin1 counteracted this suppression." (PMID 34428336, 2021). "Therefore, Skp2-deficiency may suppress the increase of mesenchymal fibroblasts by BLM-administration and contribute to the suppression of the accumulation of fibrosis-associated proteins in lung tissues, thereby attenuating the progression of pulmonary fibrosis." (PMID 29415439, 2018). "Several types of chemical Skp2 inhibitors were explored as therapeutic drugs for malignant cancers, whereas there are no reports about the application of Skp2 inhibitors against pulmonary fibrosis." (PMID 29415439, 2018). "Additionally, miR‐205‐5p overexpression increased autophagy and reduced the pulmonary fibrosis, while overexpression of E2F1 or SKP2 or inhibition of Beclin1 could annul this effect." (PMID 34428336, 2021).
pulmonary fibrosis (continued). "Based on these findings, we then determined whether p27 expression was altered in BLM-induced lung fibrosis and found that p27 levels were significantly decreased by BLM-administration in WT mice, whereas p27 did not decrease in Skp2−/− mice." (PMID 29415439, 2018).
soft tissue sarcoma (7 papers, 2008 to 2025). A malignant neoplasm arising from muscle tissue, adipose tissue, blood vessels, fibrous tissue, or other supportive tissues excluding the bones. "Elevated expression of S-phase kinase-associated protein-2 (Skp2), a key regulator of S-phase entry, was found to be associated with a worse prognosis in soft tissue sarcomas." (PMID 38561375, 2024). "Oliveira found that Skp2 expression is associated with cell proliferation and a worse prognosis in 182 soft tissue sarcomas." (PMID 23071715, 2012). "The purpose of this study is to clarify the prognostic significance of expression of Jab1, p16, p21, p62, Ki67 and Skp2 in soft tissue sarcomas (STS)." (PMID 23071715, 2012). "Skp2 over-expression plays a role in aggressiveness of soft tissues sarcomas, where it has been found to be an independent prognosticator, stronger than p27Kip1 and Ki67." (PMID 18474118, 2008). "Skp2 overexpression plays a role as an independent prognosticator, stronger than p27Kip1 and Ki67, in soft tissues sarcomas." (PMID 18474118, 2008). "Moreover, SKP2, which plays a role in soft-tissue sarcoma aggressiveness, CD133, and actin have all recently been reported as potential markers of GIST prognosis." (PMID 23690967, 2013). "Future studies are warranted to evaluate whether adjuvant chemotherapy or radiotherapy will improve the poor prognosis of Skp2 expressing soft tissue sarcoma patients." (PMID 23071715, 2012). "Together, these data indicate that RCC1 knockdown suppresses the proliferation, migration and invasion of soft-tissue sarcoma cells through compromising the protein stability of Skp2, and that RCC1 and Skp2 might be functionally related in the oncogenesis of soft-tissue sarcoma." (PMID 38561375, 2024). "The purpose of this study is to clarify the prognostic significance of expression of Skp2 related to gender, estrogen receptor (ER) and progesterone receptor (PGR) in soft tissue sarcomas (STS)." (PMID 23497154, 2013). "Increased expression of Skp2 in patients with soft tissue sarcomas is an independent negative prognostic factor for disease-specific survival in women and in patients not administered chemotherapy or radiotherapy." (PMID 23071715, 2012). "Finally, we validated that suppression of RCC1 could significantly inhibit the growth of soft-tissue sarcoma in vivo, which was largely compromised by introduction of nondegradable form of Skp2." (PMID 38561375, 2024).
squamous cell carcinoma (7 papers, 2013 to 2023). A carcinoma arising from squamous epithelial cells. "Both MCM2 and SKP2 are implicated in the G1/S phase transition of the mitotic cell cycle and are reported to be co-expressed in lung and squamous cell carcinoma tissue samples, showing the close relationship between these two proteins." (PMID 33339207, 2020). "In squamous cell carcinoma, the higher expression of TS and activity of Skp2, the enzymes synthesizing thymidine monophosphate (TMP), decreases the efficacy of pemetrexed." (PMID 29291705, 2018). "Oncogenic role of Skp2 is well established in the malignancies of head and neck ranging from squamous cell carcinoma to melanoma." (PMID 30333956, 2018). "Nevertheless, it is has been shown that Skp2 nuclear protein expression have prognostic impact in some human cancers such as squamous cell carcinoma." (PMID 23385514, 2013). "Altogether, these data suggest an important function for curcumin, acting as a suppressor of oncoprotein Skp2 in squamous cell carcinoma cells in both HPV+ and HPV− cells; raise the possibility that this agent may have a future therapeutic role in squamous cell carcinoma." (PMID 30333956, 2018). "Altogether, these data suggest a novel function for curcumin, acting as a suppressor of oncoprotein Skp2 in squamous cell carcinoma cells, and raise the possibility that this agent may have a future therapeutic role in squamous cell carcinoma and possibly other malignancies." (PMID 30333956, 2018).